IL13 (interleukin 13)
Diseases named in the same sentence as IL13 in open-access papers (continued):
Sharing a sentence is not in itself a finding about the gene and the disease.
asthma (continued). "IL-13 is especially involved in the regulation of eosinophil infiltration, IgE synthesis, goblet cell hyperplasia, mucus hypersecretion, and sub-epithelial fibrosis in asthma." (PMID 21896169, 2011). "Promising research suggests that the interleukin-13 pathway may be an important target in the treatment of the different asthma phenotypes." (PMID 23283176, 2011). "Enhanced production of IL-13 in response to chlamydial infection may contribute to the induction and exacerbation of asthma." (PMID 21573182, 2011). "Polymorphisms in the IL-13 gene associated with asthma are described at Arg130Gln (rs20541) (also described as Arg164Gln, Gln110Arg, +2044 NIaIV RFLP, and Arg144Gln based on IPI, Unit-ProtKB/Swiss-Prot, EMBL CDS databases) in a coding region of the IL-13 gene." (PMID 23283176, 2011). "Inflammation, remodeling, and AHR, all features of asthma, are induced by IL-13 overexpression." (PMID 23283176, 2011). "IL-4 and IL-13 were shown to induce AHR in mouse asthma models." (PMID 21437195, 2011). "The effects of gender and asthma on IL-13+ T cells could be either from epigenetic, developmental imprinting from continuous hormone exposure, or, alternatively, from acute stimulation by hormones before blood draw." (PMID 20667106, 2010). "Administration of recombinant IL-13 directly to the mouse airway, or transgenic over-expression of IL-13 in the airway, is sufficient to induce a phenotype resembling human asthma pathology, characterised by eosinophilia, airway remodelling, goblet cell upregulation, mucus hypersecretion and AHR." (PMID 20957211, 2010). "IL-13 levels are increased in the airways of patients with asthma." (PMID 20064211, 2010). "It has been shown that IL-4, IL-5 and IL-13, the well-defined Th2 cytokines, play an important role in the pathophysiology of allergic diseases including asthma These Th2 cytokines were significantly decreased in CC10-Smad7 mice compared to the wild type animals." (PMID 20405019, 2010). "Inflammatory mediator release including Th2 cytokines (IL-4 and IL-13), and lipid eicosanoids (prostaglandins, leukotrienes and lipoxins), from eosinophils also contribute to the clinical symptoms of asthma through their potent effects on airway vascular tissue and smooth muscle reactivity." (PMID 19769993, 2010). "The importance of these factors has further been figured out in mouse models of experimental asthma: neither in animals deficient for IL-4 or IL-13 nor in animals deficient for the IL-5 receptor it was possible to induce allergic airway inflammation or AHR." (PMID 20976014, 2010). "Therefore, we submitted Cerk-/- mice to an ovalbumin-induced asthma model, where cytokines such as IL-4 and IL-13 are playing key roles." (PMID 20053284, 2010). "For example, since IL-13 might generate adverse effects, such as induction of allergy or asthma, and a profibrotic effect of IL-13 secreted by hepatic iNKT cells has been suggested in the context of chronic HCV infection." (PMID 21179412, 2010). "STAT-6 mediates many of the biological effects of IL-13 during asthma pathogenesis and fibrosis." (PMID 20738867, 2010). "The potential of Th2 cells to promote allergic immunopathology is amplified by production of a range of mediators including IL-4, IL-5, IL-9, IL-13 and IL-25 which together promote the salient feature of asthma such as IgE production, AHR, inflammation and tissue remodelling." (PMID 19769993, 2010). "Furthermore our data support the evidence that IL-13 is important for the late phase decline in lung function in preclinical models and in asthma patients." (PMID 20957211, 2010). "Frequencies of CD4+ and CD8+ T cells producing IL-4, IL-13 after in vitro stimulation were significantly higher in asthma patients than in the control group (IL-4: P < .00001, P < .00003 for CD4+ and CD8+ T cells, resp., IL-13: P < .00001 for CD4+ and CD8+ T cells)." (PMID 21197090, 2010).
asthma (continued). "To test our hypothesis we measured serum concentrations of eleven cytokines and chemokines that were recently described to play an important role in asthma pathogenesis: IL-4, IL-5, IL-8, IL-10, IL-12 (p40), IL-13, IL-17, TNFα, GM-CSF, eotaxin, and IFNγ." (PMID 21179211, 2010). "Nevertheless our data is consistent with previous reports showing that over expression of IL-13 did not alter IL-5 expression in mouse lung, nor was it affected by IL-13 genetic deficiency in a mouse asthma model." (PMID 20573261, 2010). "For example, during asthma, infiltrating Th2 lymphocytes produce interleukin-13 (IL-13), a key cytokine that mediates multiple phenotypes of airway remodeling, including mucus cell metaplasia, eosinophilia, airway smooth muscle thickening and airway fibrogenesis." (PMID 20738867, 2010). "This suggests that the increased IL-13 expression in asthma may be mediated by a hitherto undetermined pro-inflammatory stimulus in asthmatic serum." (PMID 19602238, 2009). "However, we are confident that we have established key differences in IL-13 expression between asthma and EB by peripheral blood T-cells supporting the view that the differences observed in the airway and also present systemically." (PMID 19602238, 2009). "In conclusion we have found that IL-13 expression is increased in peripheral blood T-cells in asthma compared to EB and healthy subjects, which in part may be due to a pro-inflammatory stimulus in asthmatic serum." (PMID 19602238, 2009). "Its central role in the asthma paradigm is supported by human studies that have reported increased IL-13 mRNA expression in bronchial biopsies from subjects with moderate asthma and from sputum cells from corticosteroid naïve and inhaled corticosteroid treated asthmatics." (PMID 19602238, 2009). "This suggests that the observed up-regulation of the IL-13 axis by airway eosinophils in asthma may be influenced by the local microenvironment." (PMID 19602238, 2009). "PCR products for IL-5 and IL-13 amplified from lung cell RNA preparations were decreased in the PT, CR and their combinational prescription-treated mice compared with control mice (ova-induced asthma model mice group)." (PMID 19657453, 2009). "Finally, we have shown a role for arginase in IL-13 induced airway hyperresponsiveness and others have recently suggested a role for arginase in mouse and guinea pig asthma models using arginase inhibitors." (PMID 19486531, 2009). "We hypothesised that IL-13 expression is upregulated in peripheral blood T-cells and eosinophils in asthma compared to EB and healthy controls." (PMID 19602238, 2009). "Both Il-4 and IL-13 are cytokines associated with the inflammatory process in diseases such as asthma, but neither of these cytokines has chemokine properties." (PMID 19772569, 2009). "Animal data indicate that IL-9 can promote asthma through IL-13-independent pathways via expansion of mast cells, eosinophils, and B cells, and through induction of IL-13 production by hemopoietic cells for mucus production and recruitment of eosinophils by lung epithelial cells." (PMID 18315837, 2008). "The aim of this study was to investigate whether there is a combined effect of interleukin-13 gene (IL13) polymorphisms and tobacco smoke on persistent childhood wheezing and asthma." (PMID 18186920, 2008). "Tobacco smoke exposure after pregnancy did not modify the association of IL13 and wheezing nor asthma." (PMID 18186920, 2008). "Animal models demonstrate a role for IL-13 in the development of airway hyperresponsiveness (AHR); overexpression of IL-13 in the murine lung induces a phenotype similar to human asthma, with excess mucus production, goblet cell hyperplasia, smooth muscle hypertrophy and AHR." (PMID 19116009, 2008). "IL-13 has diverse effects on HASM cells that may have important implications for the pathobiology of asthma." (PMID 19116009, 2008).
asthma (continued). "In addition, Centocor has developed an anti-human IL-13 antibody that is effective in animal models of asthma and IMA-638 (IgG1, kappa), a humanized antibody to human IL-13 from Wyeth Research is effective in animal models of asthma." (PMID 18315837, 2008). "We conclude that IL-13 may contribute to subepithelial fibrosis in asthma by stimulating the continuous release TGF-β2 from the airway epithelium." (PMID 18348727, 2008). "IL-4 and IL-13 are interesting targets for allergy and asthma therapies." (PMID 16640778, 2006). "Our present study further supports the concept that IL-13 regulates the expression of different "pro-asthmatic" genes that are potentially important in the regulation of all three key features of asthma, i.e., airway inflammation, airway remodeling and bronchial hyper-responsiveness." (PMID 15661077, 2005). "Although the underlying mechanisms remain unknown, a number of reports have shown that IL-13 may exert its deleterious effects in asthma by directly acting on airway resident cells, including epithelial cells and airway smooth muscle cells." (PMID 15661077, 2005). "Although the functional relevance of such gene microarray analyses remains yet uncertain, these studies strongly suggest that IL-13 may be involved in the pathogenesis of asthma by directly modulating physiological responses of the ASM." (PMID 15661077, 2005). "In this report, we hypothesize that IL-13 may participate in the pathogenesis of asthma by activating a set of "pro-asthmatic" genes in airway smooth muscle (ASM) cells." (PMID 15661077, 2005). "Identifying the expression profile of "pro-asthmatic" genes activated by IL-13 in ASM cells may therefore provide new insight into the design of novel therapeutic approaches for asthma." (PMID 15661077, 2005). "IL-13 may exert its deleterious effects in asthma by directly altering gene expression in airway resident cells such as epithelial cells or ASM cells." (PMID 15661077, 2005). "The stimulatory role of IL-13 on VCAM-1 may be important in asthma since VCAM-1 has been regarded as a key player in the development of airway inflammation." (PMID 15661077, 2005). "Ten hub genes (including TNF, IL5, IL13, TLR4) were linked to 339 potential therapeutic agents; the exploratory network analysis highlighted overlap between predicted miRNA-regulated hub genes and existing asthma-relevant drug targets, including approved biologics." (PMID 42042546, 2026). "Significant improvements in FEV1 (MD, 0.11; 95% CI, 0.10 to 0.11), Asthma Control Questionnaire scores (MD, −0.20; 95% CI, −0.22 to −0.18), and annual exacerbation rates (MD, −0.15; 95% CI, −0.16 to −0.14) were also seen with anti–IL-4/IL-13 biologic therapies." (PMID 39844912, 2025). "The current biologics for severe asthma treatment include omalizumab (anti-IgE), mepolizumab and reslizumab (anti-IL-5), benralizumab (anti-IL-5 receptor), dupilumab (anti-IL-4 receptor α, blocking both the IL-4 and IL-13 pathways), and tezepelumab (anti-TSLP)." (PMID 40364184, 2025). "Let-7 miRNAs have been found to be downregulated in asthma, and emerging evidence suggests they may contribute to sex disparities in the disease; in fact, Let-7 miRNAs regulate IL-13 expression, which, as mentioned in the pathophysiology, covers a central role in type 2 inflammation." (PMID 40508095, 2025). "Similarly, asthma patients with elevated IL-13 have reduced SPLUNC1 protein in their sputum." (PMID 40589325, 2025). "The Th2 cytokines seen in asthma, especially IL-4 and IL-13, may downregulate the Th1 immune response, potentially offering a protective mechanism against COVID-19 and could provide an explanation as to why asthmatic patients infected with SARS-CoV-2 have better disease outcomes." (PMID 40004141, 2025). "Furthermore, in vitro experiments demonstrated that UC-MSCs could directly reduce the secretion of IL-5 and IL-13 in Th2 cells and peripheral blood mononuclear cells (PBMCs) from mice model of asthma." (PMID 41309530, 2025).
asthma (continued). "IL-13–mediated MTOR activation drives loss of control of airway epithelial cell proliferation, hypertrophy, and migration, contributing to airway wall thickening and formation of eGC (eGC), which are key features of mucous cell metaplasia found in severe asthma." (PMID 40446022, 2025). "For instance, tauroursodeoxycholic acid (TUDCA) significantly reduces HDM-induced IL-4, IL-5, IL-13, and IgE levels, whereas β-muricholic acid suppresses IL-6 and IL-33 production, underscoring the diverse metabolic pathways through which gut microbes influence asthma pathogenesis." (PMID 41229685, 2025). "In addition, in chronic asthma, Th2 cells are known to infiltrate the lungs and produce inflammatory cytokines, such as IL-4, IL-5, and IL-13, which are crucial in initiating and progressing allergic diseases, including asthma, by driving Th2-mediated immune responses." (PMID 40622480, 2025). "However, studies in asthma and other inflammatory diseases suggest that genetic variations in cytokines such as IL-5, IL-4, IL-13, and TNF may influence responses to biologic therapies." (PMID 40149465, 2025). "Furthermore, no secretion of asthma-associated cytokines such as IL-4 or IL-13 was observed in response to hPIV-3 infection (data not shown)." (PMID 41239423, 2025). "Notably, only one biological agent has received approval for use in both diseases: the anti‐IL4/IL13 dupilumab is effective at reducing exacerbation rates and maintenance oral corticosteroid (mOCS) use in severe asthma, and it also significantly reduces disease burden in atopic dermatitis." (PMID 40662227, 2025). "Additionally, elevated Th2 cytokines such as IL-4 and IL-13 in poorly controlled asthma may upregulate IgE synthesis and mast cell activation, further compounding the risk of anaphylactic shock." (PMID 40917873, 2025). "IL-13 is a key cytokine involved in the formation of mucus plugs; there is therefore a need for large-scale studies examine whether dupilumab is an effective therapeutic option for mucus plugs in patients with asthma." (PMID 41440490, 2025). "Additionally, IL-13 can enhance the expression of nitric oxide synthase in airway epithelial cells, leading to elevated levels of exhaled nitric oxide (FeNO), a marker often utilized to identify T2-high asthma." (PMID 40564060, 2025). "Dupilumab is a fully human monoclonal antibody that blocks the shared receptor component for IL-4 and IL-13, inhibiting the signalling of both IL-4 and IL-13, which are key and central drivers of type 2-mediated inflammation in multiple allergic diseases, especially in AD and asthma." (PMID 39340076, 2024). "Moreover, a study with IL-4- and IL-13-treated macrophages stimulated with IL-33 (an asthma cellular model) induced an increase in the expression of miR-155-5p, along with an increase in inflammatory mediators (Ccl3, Ccl5, Ccl17, Ccl24, and Il1b) compared to macrophages without pretreatment." (PMID 38337625, 2024). "In addition, anti-IL-13 therapy plays a significant role in targeted asthma therapy." (PMID 38218943, 2024). "Furthermore, IL-4 and IL-13 play a critical role in asthma pathobiology." (PMID 39188724, 2024). "Similarly, in asthma, viral infections trigger robust immune responses characterized by eosinophilic inflammation and the production of Th2 cytokines, including IL-4, IL-5, and IL-13." (PMID 39458339, 2024). "In asthma, there were variations in ACE2 expression due to different asthma endotypes which can influence COVID-19 susceptibility, with IL-17 potentially upregulating ACE2 expression, while IL-4 and IL-13 may downregulate it." (PMID 38899005, 2024). "Further, inhibition of IL-13–mediated signaling can reverse goblet cell hyperplasia, suggesting that IL-13 may contribute to the pathophysiology of airway diseases such as asthma and COPD." (PMID 39255033, 2024). "Furthermore, IL-13 was significantly increased in patients with comorbid asthma." (PMID 38850424, 2024).
asthma (continued). "Notably, treatment with BXM significantly ameliorated asthma symptoms, including less lung inflammation, mucus secretion, and the generation of Th2 cytokines (IL-5, IL-13, and IL-4), which were dramatically attenuated by anti-VISTA monoclonal antibody treatment." (PMID 38340268, 2024). "However, in our study, IL-13 and IL-17 levels were lower in the asthma group." (PMID 38218943, 2024). "In this sense, asthma is a respiratory disease characterized by a chronic inflammation including the activation of the Th2 cell response to allergens, and is often found to have elevated levels of inflammatory cytokines including IL-4, IL-5, IL-13, TNF-α, and IL-1β, among others." (PMID 38792145, 2024). "Circ_0005519 may increase IL-13/IL-6 level by adjusting let-7-a-5p to affect asthma." (PMID 38521909, 2024). "In the present study, we suspect that monoclonal antibodies targeting IL-4 and/or IL-13 may inhibit central processes that improve outcomes in patients with or without mixed phenotypes that may have a reduced capacity for response to baseline asthma therapies." (PMID 37901346, 2023). "Moreover, a significant decrease in IL-13, responsible for mucus hypersecretion, goblet cell metaplasia, non-specific airway hyperreactivity, fibrosis, IgE production, and asthma, pave the ability of AR-B to be used in IL-13 restraining approach to overcome lung fibrosis." (PMID 36820943, 2023). "Additionally, IL-13, IL-5 and IL-9 are also important in this process, aiding in the recruitment of eosinophils and mast cells, culminating in increased bronchial hyperresponsiveness - an essential feature of asthma." (PMID 37841931, 2023). "Moreover, levels of DPP4 in the serum samples of asthma patients have been proposed as a type 2 inflammation marker and may predict the therapeutic efficacy of an IL-13 neutralizing antibody in a clinical trial." (PMID 37287831, 2023). "Although ADNP has not been identified as a common factor in asthma susceptibility, unlike IL-4, IL-5, and IL-13, it was reported among a subset of genes that were differentially expressed by CD4+ lymphocytes and that predicted more atopic from less atopic children." (PMID 37285842, 2023). "Type 2 (T2) inflammation is the most common endotype in both asthma and CRSwNP Caucasian populations, and it is characterized by the presence of Th2 and T2 innate lymphoid cells that secrete T2 cytokines (IL-4, IL-5, and IL-13), eosinophilia, and high IgE titers." (PMID 37088840, 2023). "Kyoto Encyclopedia of Genes and Genomes (KEGG) pathway analysis indicated that the differentially expressed genes (DEGs) downregulated in the absence of ADNP were associated with “Asthma” pathways, which correlates with the roles of IL-13 and Th2 cells in allergic asthma." (PMID 37285842, 2023). "Our data showed that airways and tissue eosinophilia, as well as the expression of total IgE, OVA‐specific IgE, IL‐13 and IL‐33 in response to OVA challenge, were inhibited by serial CSE exposure, which may be associated with difficult‐to‐treat asthma with smoking." (PMID 37963721, 2023). "IL-4 and IL-13 were found to downregulate polymeric immunoglobulin receptor (pIgR) at the site of IgA binding on airway epithelial cells, suggesting that IgA levels may be reduced in asthma." (PMID 37445635, 2023). "Interestingly, either the overexpression of Nr1d1 or the treatment with its ligand (SR9011) protected mice against lung inflammation in an asthma model (as shown by lung histology, reduced histological scores, IL-4-, IL-5-, and IL-13-levels, as well as reduced GATA3 expression) [37••]." (PMID 36520269, 2023). "In conclusion, inhibition of IL-4 and IL-13, and to a lesser degree inhibition of IL-13 alone, may benefit patients with T2 high asthma, such as those with elevated FeNO levels, elevated blood eosinophils (≥300 cells/μL) or sputum eosinophils (≥3%), and/or elevated periostin." (PMID 40980110, 2023).